SMU1 (SMU1 DNA replication regulator and spliceosomal factor)
Description:
Involved in pre-mRNA splicing as a component of the spliceosome. Regulates alternative splicing of the HSPG2 pre-mRNA (By similarity). Required for normal accumulation of IK. Required for normal mitotic spindle assembly and normal progress through mitosis (By similarity). (Microbial infection) Required, together with IK, for normal splicing of influenza A virus NS1 pre-mRNA, which is required for the production of the exportin NS2 and for the production of influenza A virus particles. Not required for the production of VSV virus particles.
Synonyms: SMU-1; FLJ10805; BWD; fSAP57
Tractability: Small molecule: a structure with a bound ligand is known. PROTAC: UniProt records ubiquitination sites on it; ubiquitination databases record sites on it; its protein half-life has been measured.
Target class: Reader; Epigenetic regulator; Methyl-lysine/arginine binding protein; WDR domain
Gene: Protein-coding gene on chromosome 9 (33,041,765 to 33,076,694, reverse strand). Ensembl gene ENSG00000122692.
Subcellular location: Cytoplasm; Nucleus; Nucleus speckle
Subcellular location (Human Protein Atlas): Vesicles
Pathways (Reactome):
Metabolism of RNA: mRNA Splicing - Major Pathway
Gene Ontology:
Molecular function: protein binding
Biological process: mRNA splicing, via spliceosome; regulation of alternative mRNA splicing, via spliceosome
Cellular component: nucleus; U2-type precatalytic spliceosome; cytoplasm; nuclear speck; nucleoplasm; precatalytic spliceosome
Genetic constraint (gnomAD): Loss-of-function variants: 2 observed, 63.58 expected, observed/expected ratio (o/e) 0.0315, 90% interval 0.012 to 0.099. The upper end of that interval is the gene's LOEUF score, 0.099, which puts it in group 1 of 6, group 1 being the genes least tolerant of losing a copy. Missense variants: 225 observed, 633.35 expected, observed/expected ratio (o/e) 0.36, 90% interval 0.32 to 0.4. Synonymous variants: 185 observed, 217.35 expected, observed/expected ratio (o/e) 0.85, 90% interval 0.75 to 0.96.
Homologues: Orthologues: chimpanzee SMU1 (100% identical), dog SMU1 (100% identical), guinea pig SMU1 (100% identical), macaque SMU1 (100% identical), mouse Smu1 (100% identical), pig SMU1 (100% identical), rat Smu1 (100% identical), tropical clawed frog smu1 (99% identical), rabbit SMU1 (98% identical), zebrafish smu1a (96% identical), Drosophila melanogaster Smu1 (78% identical), zebrafish smu1b (76% identical), and 1 more.
Diseases named in the same sentence as SMU1 in open-access papers:
SMU1 is named in the same sentence as 7 diseases in open-access papers, as found by Europe PMC text mining. Sharing a sentence is not in itself a finding about the gene and the disease. The quoted sentences say what the papers report.
3M syndrome (1 paper, 2025). 3M syndrome is a primordial growth disorder characterized by low birth weight, reduced birth length, severe postnatal growth restriction, a spectrum of minor anomalies (including facial dysmorphism) and normal intelligence. "We found SMU1 to be associated with 3M syndrome, and TCOF1 to be associated with BBSome complex responsible for Bardet Biedl syndrome." (PMID 41312386, 2025).
gastric carcinoma (1 paper, 2026). A carcinoma that arises from epithelial cells of the stomach. "Experimental evidence also confirms that SMU1 knockdown significantly inhibits gastric carcinoma growth, migration, and invasion." (PMID 41511464, 2026).
glioma (1 paper, 2022). A benign or malignant brain and spinal cord tumor that arises from glial cells (astrocytes, oligodendrocytes, ependymal cells). "The qRT-PCR results showed that the mRNA expression levels of FAM204A and SMU1 in human glioma cell lines overall showed a downward trend compared with the HA1800, while the mRNA expression levels of TNPO1 and TOP2A showed an overall upward trend." (PMID 35093128, 2022).
tumor (4 papers, 2015 to 2026). "We selected four LLPS-related hub genes (FAM204A, SMU1, TNPO1 and TOP2A) involved in LPRS to test their transcript levels in cell lines, LGG tissues and non-tumor brain tissues." (PMID 35093128, 2022). "Compared with non-tumor brain tissue, the transcription levels of FAM204A and SMU1 in LGG tissues decreased, while the transcription levels of NPO1 and TOP2A increased." (PMID 35093128, 2022).
cancer (2 papers, 2019 to 2026). A tumor composed of atypical neoplastic, often pleomorphic cells that invade other tissues. "This pattern suggests that while the driver component of SMU1 potentially exerts context-dependent oncogenicity, its native function appears indispensable for cancer cell survival." (PMID 41511464, 2026). "Functionally, as a chromatin-binding protein involved in DNA replication regulation and spliceosome activation, SMU1 demonstrates remarkable essentiality, with an average CERES score of −2.63 and is essential in 99.8% (1079/1081) cancer cell lines." (PMID 41511464, 2026).
infection (1 paper, 2014). The state of being infected such as from the introduction of a foreign agent such as serum, vaccine, antigenic substance or organism. "This is in agreement with our observation that the accumulation of other viral mRNAs and proteins (NS1, M1, M2, NP) was reduced at early stages of infection in cells silenced for RED or SMU1, which could be a consequence of the low levels of NS2 synthesis." (PMID 24945353, 2014). "Total cell extracts were prepared at various times post-infection and were analyzed by western blot using anti-RED, anti-SMU1 and anti-NP antibodies." (PMID 24945353, 2014).
SMU1 also shares sentences with these, for which no sentence is quoted: Bardet-Biedl syndrome (1 paper).